MTCO1P12 (MT-CO1 pseudogene 12)
Gene: Unprocessed pseudogene on chromosome 1 (631,074 to 632,616, forward strand). Ensembl gene ENSG00000237973.
Diseases named in the same sentence as MTCO1P12 in open-access papers:
MTCO1P12 is named in the same sentence as 3 diseases in open-access papers, as found by Europe PMC text mining. Sharing a sentence is not in itself a finding about the gene and the disease. The quoted sentences say what the papers report.
inflammatory bowel disease (1 paper, 2023). A spectrum of small and large bowel inflammatory diseases of unknown etiology. "MTCO1P12 is a mitochondrially encoded pseudogene that has been reported to be severely downregulated in inflammatory bowel disease, associated with reduced mitochondrial energy production." (PMID 36282542, 2023).
schizophrenia (1 paper, 2024). A major psychotic disorder characterized by abnormalities in the perception or expression of reality. "From total 66 DEGs, we identified 11 (16%) as pseudogenes, which comprised two main groups: mitochondrial pseudogenes increased in females (MTND1P23, MTCO1P12, MTCO1P40, and MTND2P28) and ribosomal pseudogenes increased in male schizophrenia patients (RPS4XP22, RPS16P4, and RPS28P7)." (PMID 39068467, 2024).
MTCO1P12 also shares sentences with these, for which no sentence is quoted: depression (1 paper).